ZFX (zinc finger protein X-linked)
Diseases named in the same sentence as ZFX in open-access papers (continued):
Sharing a sentence is not in itself a finding about the gene and the disease.
endometrial carcinoma (2 papers, 2014 to 2020). A malignant tumor arising from the epithelium that lines the cavity of the uterine body. "Finally, a solitary ZFX R786Q somatic mutation in endometrial carcinoma has been registered in the COSMIC database (endometrial cancer; mutation ID: COSM1119462)." (PMID 25594030, 2014). "Further, we found that miR-302c-3p exerts its effect on the biological behavior of endometrial cancer by regulating ZFX." (PMID 32760226, 2020). "It has been demonstrated that ZFX expression is higher in endometrial cancer than in normal endometrium." (PMID 32760226, 2020). "Our study also revealed that YKL-40 is positively regulated by ZFX and promotes type I endometrial cancer development." (PMID 32760226, 2020). "Further investigation into this regulatory mechanism indicated that ZFX is highly expressed in endometrial cancer tissues and promotes the proliferation and invasion of type I endometrial cancer cells." (PMID 32760226, 2020). "MiR-302c-3p acts as a tumor suppressor in endometrial cancer and inhibits type I endometrial cancer development by regulating the transcription factor ZFX and its downstream protein YKL-40." (PMID 32760226, 2020). "Our study revealed that ZFX is highly expressed in endometrial cancer and promotes endometrial cancer cell proliferation and invasion." (PMID 32760226, 2020). "Transwell assays revealed that when ZFX was upregulated, the invasive ability of endometrial cancer cells increased, whereas the invasive ability decreased following ZFX downregulation." (PMID 32760226, 2020). "As miR-302c-3p target, ZFX is involved in the effect of HOXA-AS2 on endometrial cancer progression." (PMID 32760226, 2020). "We test expression levels of HOXA-AS2, miRNA-302c-3p, the transcription factor zinc finger X-chromosomal protein (ZFX), and the chitinase-like protein YKL-40 in endometrial carcinoma by qRT-PCR and western blotting." (PMID 32760226, 2020). "In type I endometrial cancer cells, YKL expression was regulated by ZFX, HOXA-AS2, and miR-302c-3p at both the protein and mRNA levels." (PMID 32760226, 2020). "Using qRT-PCR and western blotting, we found that ZFX and YKL-40 were significantly higher in endometrial cancer tissues than in normal endometrial tissues both mRNA and protein levels." (PMID 32760226, 2020).
leukemia (2 papers, 2012 to 2023). A malignant (clonal) hematologic disorder, involving hematopoietic stem cells and characterized by the presence of primitive or atypical myeloid or lymphoid cells in the bone marrow and the blood. "Transgenic mouse studies indicate that ZFX facilitates tumorigenesis, which is further supported by studies on various human tumors, including leukemia." (PMID 37864206, 2023). "However, the role of ZFX in leukemia stem/progenitor cells has not been investigated." (PMID 37864206, 2023).
liver cancer (2 papers, 2014 to 2017). An epithelial or non-epithelial malignant neoplasm that arises from the liver. "However, the role of ZFX in liver cancer stem cells (CSCs) remains obscure." (PMID 28156061, 2017). "To address this issue, we determined the expression level of ZFX in EpCAM+ subpopulation sorted from cultured HCC cell lines (SMMC‐7721, HepG2, and Huh7) or primary liver cancer cells." (PMID 28156061, 2017).
ovarian failure (2 papers, 2012 to 2025). "ATP7A and PHKA1 are likely related to the cardiovascular system, EBP is associated with coronary heart disease and skeletal-related conditions, ZFX is known to be involved in animal size and ovarian failure, and SMC1A is implicated in premature ovarian failure." (PMID 39940742, 2025). "However, haploinsufficiency for the ZFX gene (X-linked zinc finger protein at Xp21.2) may be an important factor as it has been identified as a candidate gene for ovarian failure." (PMID 22794123, 2012).
pancreatic cancer (2 papers, 2020 to 2021). "In contrast, NDRs in primary pancreatic cancer-specific enhancers involved in enhancer-promoter loops are enriched for motifs for TFs such as E2F1, MAZ, and ZFX." (PMID 34348759, 2021).
renal carcinoma (2 papers, 2018 to 2025). A carcinoma arising from the epithelium of the renal parenchyma or the renal pelvis. "This regulatory effect of ZFX may be one of the reasons why genetic manipulations to silence ZFX in breast, colorectal, pancreatic, and renal cancers reduced proliferation and predicted good prognosis." (PMID 40934285, 2025). "Also, knockdown of ZFX expression in renal carcinoma cells results in significantly inhibited proliferation and cell cycle progression." (PMID 29429977, 2018).
renal cell carcinoma (2 papers, 2018 to 2019). "Finally, ZFX is significantly up-regulated in renal cell carcinomas (RCC) and has been suggested to be a strong predictor for prognosis of RCC patients." (PMID 29429977, 2018).
acute myeloid leukemia (1 paper, 2015). Acute myeloid leukemia (AML) is a group of neoplasms arising from precursor cells committed to the myeloid cell-line differentiation. "Furthermore, ZFX protein has been implicated in acute myeloid leukemia (AML) and acute T-lymphoblastic leukemia (T-ALL)." (PMID 25916205, 2015).
adenoma (1 paper, 2014). A neoplasm arising from the epithelium. "In our whole-exome sequencing, samples harboring somatic ZFX mutations did not overlap with those containing somatic mutations in MEN1, which were detected in 2 of the 19 sporadic adenomas." (PMID 25594030, 2014).
brain tumor (1 paper, 2018). "This motif was originally identified from ZNF711 ChIP-seq data from the brain tumor cell line SH-SY5Y and from ZFX ChIP-seq data from mouse embryonic stem cells." (PMID 29429977, 2018).
breast tumors (1 paper, 2019). "In this study, we investigated the potential expression of different variants of ZFX in human breast tumors and a series of stem and cancer cell lines to evaluate the variants manner." (PMID 29753316, 2019). "The distinctive expression patterns of ZFX variants may be useful in discriminating the different types of breast tumors." (PMID 29753316, 2019). "Moreover, the expression level of ZFX variant 4 was significantly higher in ductal breast tumors in comparison to lobular tumors (p < 0.05)." (PMID 29753316, 2019). "The correlation between tumor stages and ZFX variant expressions was assessed and showed that, contrary to the ZFX variant 1/3, the highest level of ZFX variant 4 and ZFX variant 5 expression was observed in stage III breast tumors." (PMID 29753316, 2019).
cervical carcinoma (1 paper, 2018). A carcinoma arising from either the exocervical squamous epithelium or the endocervical glandular epithelium. "Upregulated zinc finger protein X-linked (ZFX) and cervical carcinoma expressed PCNA regulatory lncRNA (CCHE1) increase cell cycle progression and decrease apoptosis to stimulate proliferation because of their similar mechanisms in GC and HCC, respectively." (PMID 29736267, 2018).
cervical tumor (1 paper, 2019). "Proteins such as STAT3, TGFβ3, LEFTY A, PARP1, and ZFX are also expressed in cervical tumor samples." (PMID 31885625, 2019).
chronic myeloid leukemia (1 paper, 2023). "However, the role of ZFX in the growth and drug response of chronic myeloid leukemia (CML) stem/progenitor cells remains unclear." (PMID 37864206, 2023).
colon cancer (1 paper, 2018). "Moreover, knockdown of ZFX suppresses proliferation and invasion of colon cancer cell lines." (PMID 29429977, 2018).
cutaneous nevi (1 paper, 2025). "Additionally, she presented other characteristics seen in patients with pathogenic variants in the ZFX gene, such as hearing loss and multiple cutaneous nevi." (PMID 40779536, 2025).
esophageal carcinoma (1 paper, 2011). A primary or metastatic malignant neoplasm involving the esophagus. "Huang D and others found that stem cell-related genes (including OCT-4, SOX-2, BMI-1, and ZFX) were upregulated in SP(side population) cells of human esophageal carcinoma 9706 cells compared with non-SP cells." (PMID 22185393, 2011).
gallbladder adenocarcinoma (1 paper, 2018). A carcinoma that arises from glandular epithelial cells of the gall bladder. "For example, ZFX expression is significantly related to histological grade (P-value <0.001) in gallbladder adenocarcinoma, and patients that survived <1 yr were found to have significantly higher ZFX expression than patients that survived >1 yr." (PMID 29429977, 2018).
lung adenocarcinoma (1 paper, 2013). A carcinoma that arises from the lung and is characterized by the presence of malignant glandular epithelial cells. "Also, the relative expression levels of ZFX in low-grade (IA-IIB) and high-grade (IIIA-IV) lung adenocarcinoma were also compared." (PMID 24066116, 2013).
lung carcinoma (1 paper, 2013). "However, there is still lack of data on the role of ZFX on lung cancer behavior and mir-144-ZFX pathway has never been reported in context of NSCLC." (PMID 24066116, 2013).
myelodysplastic syndrome (1 paper, 2021). A clonal hematopoietic disorder characterized by dysplasia and ineffective hematopoiesis in one or more of the hematopoietic cell lines. "By exome sequencing of in vitro expanded mesenchymal stromal cells (MSCs) from n = 98 patients with myelodysplastic syndrome (MDS) and n = 28 healthy controls we show that these cells accumulate recurrent mutations in genes such as ZFX (n = 8/98), RANK (n = 5/98), and others." (PMID 34697318, 2021).
osteosarcoma (1 paper, 2013). A usually aggressive malignant bone-forming mesenchymal neoplasm, predominantly affecting adolescents and young adults. "Expression of ZFX was observed in the three different Osteosarcoma cell lines, however, the expression levels of ZFX protein in Saos-2 cells were significantly higher than that in SW1351 and U2OS cells." (PMID 24353675, 2013). "Expression of ZFX protein in different Osteosarcoma cells: To determine the expression levels of ZFX in different Osteosarcoma cell lines (SW1351, Saos-2, and U2OS cells), Western blot assay was performed." (PMID 24353675, 2013). "As a result, we found that ZFX is a novel regulator, which modulates the proliferation and migration capabilities of Osteosarcoma cells via arrested G0/G1 phase cell cycle arrest and apoptosis." (PMID 24353675, 2013). "Collectively, these findings represent the first report that ZFX is a novel proliferation regulator in Osteosarcoma tumor." (PMID 24353675, 2013). "Our observation is consistent with the previous report and emphasized that ZFX facilitates important regulatory roles in Osteosarcoma cell proliferation and invasiveness." (PMID 24353675, 2013). "In this regard, we adopted a lentiviral vector-mediated RNAi system to further determine the roles of ZFX in the growth and invasive ability of Osteosarcoma cells." (PMID 24353675, 2013). "There was an obvious difference in the cell population at sub-G1 phase between the two groups, suggesting that down regulation of ZFX expression might trigger apoptosis in Osteosarcoma cells." (PMID 24353675, 2013). "Here, we first conducted an expression analysis of ZFX in Osteosarcoma cell lines." (PMID 24353675, 2013). "Hence, this study extends our knowledge about the oncogenesis of Osteosarcoma, and indicates that ZFX may serve as a new molecular target." (PMID 24353675, 2013). "Consequently, this led to a hypothesis that as an indispensible subunit of cohesin complex, ZFX may play a functional role in biological behavior of Osteosarcoma." (PMID 24353675, 2013). "However, to date, the functional roles of ZFX in Osteosarcoma have not been demonstrated." (PMID 24353675, 2013).
primary hyperparathyroidism (1 paper, 2025). Hyperfunction of the parathyroid glands resulting in the overproduction of parathyroid hormone. "We present the clinical and molecular characterization of three patients diagnosed with primary hyperparathyroidism (PHPT) who have germline variants in the ZFX gene." (PMID 40779536, 2025).
squamous cell carcinoma (1 paper, 2015). A carcinoma arising from squamous epithelial cells. "Here, we explored the relationship between ZFX expression and squamous cell carcinoma (SCC) of the tongue." (PMID 25916205, 2015).
uterine tumors (1 paper, 2020). "Multiple deletion mutations in the mesoderm group (e.g., Deletion-3 prime UTR ADAR, BHLHE40, ZFX, etc.)mainly occur in the cases with uterine tumors." (PMID 33308219, 2020).
cancer (24 papers, 2013 to 2025). A tumor composed of atypical neoplastic, often pleomorphic cells that invade other tissues. "While several reports have determined the expression of ZFX in tumors and stem cells, there is little information about the discriminating expression of ZFX splice variants in cancer." (PMID 29753316, 2019). "ZFX is upregulated in numerous human cancers; however, whether ZFX alone is sufficient to cause malignant transformation is not clear yet." (PMID 37864206, 2023). "The mechanisms by which ZFX mutations contribute to a selective growth advantage in parathyroid, and potentially other types of tumor cells, and whether ZFX is involved in cancer stem cell renewal, remain to be elucidated." (PMID 25594030, 2014). "Two genes encoding zinc finger proteins, ZFX (X-linked) and ZNF317 (autosomal), also had a higher female sex-bias on the pan-cancer level (q-value = 2.9×10−3 and 0.065; effect size = 0.13 and 0.09)." (PMID 39975298, 2025). "ZFX is a highly conserved Zinc finger protein and oncogenic transcription factor residing on the X chromosome and is overexpressed in many cancers." (PMID 40934285, 2025). "Of the three family members, ZFX has been the most studied in relation to a variety of human cancers." (PMID 32406922, 2020). "In these previous studies, it was shown that high expression of ZFX correlates with poor survival of cancer patients." (PMID 32406922, 2020). "Previous studies demonstrated that ZFX plays an essential role in cancer initiation and progression." (PMID 31310241, 2019). "ZFX has also found to contribute to signal transduction, stress response, cell cycle regulation, and the metastasis of cancer cells." (PMID 29753316, 2019). "This functional characterization of ZFX provides important new insights into transcription, chromatin structure, and the regulation of the cancer transcriptome." (PMID 29429977, 2018). "We chose to use these cancer models because there is a strong link in these four cancer types between ZFX expression and cell proliferation, tumor development, or patient survival." (PMID 29429977, 2018). "Unlike many oncogenic TFs that bind to distal elements, ZFX binds to the majority of CpG island promoters that are active in cancer cells, and many genes with promoters bound by ZFX were down-regulated upon knockdown." (PMID 29429977, 2018). "High expression of the transcription factor ZFX is correlated with proliferation, tumorigenesis, and patient survival in multiple types of human cancers." (PMID 29429977, 2018). "Meanwhile, other investigations in different cancer cell lines also revealed that knockdown of ZFX apparently induced cell cycle arrest and inhibited cell proliferation and migration." (PMID 28156061, 2017). "So, these results suggest that ZFX upregulation in tumors is quite common and ZFX as a potential biomarker for cancer diagnosis should be investigated in the future." (PMID 25916205, 2015). "The expression level of ZFX correlates with aggressiveness and severity in many cancer types, including prostate cancer, breast cancer, human malignant glioma and leukemia." (PMID 25617627, 2015). "Expression analysis revealed that RICTOR, UGCG, and ZFX were highly expressed in cancer cells." (PMID 40934285, 2025). "Therefore, our data provided another example in which ZFX modulates the properties of cancer stem cells, in agreement with other reports." (PMID 37864206, 2023). "This suggests that ZFX may play a key role in the promoter structure, and may provide new insights into the regulation of transcription, chromatin structure, and cancer transcriptomes." (PMID 35885897, 2022). "While several reports have determined the overexpression of ZFX in a variety of somatic cancers, the expression of ZFX-spliced variants in cancer cells is not well-understood." (PMID 29753316, 2019). "Recent studies have indicated that ZFX is also expressed in cancer cells and tissues." (PMID 29753316, 2019).